AKT1 (AKT serine/threonine kinase 1)
Diseases named in the same sentence as AKT1 in open-access papers (continued):
Sharing a sentence is not in itself a finding about the gene and the disease.
tumor (continued). "Moreover, in women, there was also an association between mutations in AKT1 (CA > TG, p = 0.01), PIK3CA (A > G, p = 0.02) and BRIP (T > C, p = 0.02) genes with tumor recurrence, highlighting a highly pathogenic variant in PIK3CA gene, according to CLINVAR." (PMID 34680380, 2021). "Isorhamnetin, kaempferol, FA, calycosin, hederagenin might play an anti-tumor role through targeting AKT1, CDK1 TYMS, MAPK3, AR, respectively." (PMID 34955857, 2021). "To further determine whether BAP1 function of tumor suppression is dependent on inhibiting the Akt signaling pathway, we silenced Akt1 by lenti‐shRNAs in DU145‐shBAP1‐1# cells." (PMID 33155366, 2021). "A consensus can be drawn in that while AKT1-mediated signals are associated with cell proliferation and survival, AKT2-mediated signals are associated with metastatic progression with limited or growth inhibitory actions on the primary tumor." (PMID 33498407, 2021). "To emulate drug therapy, we systemically deleted Akt1 or Akt2 after tumor onset." (PMID 35578699, 2021). "Next, we investigated the mRNA levels of PTEN/PIK3A/AKT1 in different tumor cells." (PMID 33967754, 2021). "These mutations were mutually exclusive and only one tumor harbored NF2 and AKT1 mutations." (PMID 33772057, 2021). "Univariate and multivariate analyses showed that AKT1 expression along with tumor stage could be used as independent factors to predict the overall survival of HCC patients." (PMID 33511213, 2021). "Our data suggest a significant role for Akt1 in tumor cell migration and invasion." (PMID 34394377, 2021). "In contrast, Toulany and colleagues showed that knockdown of Akt1 and to some extent Akt3, but not Akt2, inhibited cell proliferation and tumor growth in K-Ras-mutated MDA-MB-231 cells." (PMID 34298660, 2021). "AKT1 expression was related to tumor size (p=0.007), WHO grade (p=0.022) and OS (p=0.034)." (PMID 34475988, 2021). "The function of Akt1 and Akt2 in tumor progression and metastasis is debatable." (PMID 34298660, 2021). "In summary, our study proposes that the activation of the EGFR/PI3K/AKT1/NRF2 pathway by HPV16 E7 leads to PIR/NF-κB activation in tumor oral epithelial cells, resulting in an increased cell migration, with the possibility remaining that this mechanism is involved in other epithelial cell models." (PMID 32679705, 2020). "Our data suggest that miR-3135b is a novel tumor suppressor with a potential role in the regulation of the GOLPH3/AKT1/mTOR axis to maintain Golgi integrity, which adds a piece in the puzzle of the novel cytoplasmic DNA damage response to DNA-damaging agents in CRC cells." (PMID 32601379, 2020). "However, we show the potential for the selective sensitization of tumor cells to radiation therapy with timed knockdown of Akt1 expression after radiation therapy." (PMID 32438621, 2020). "In Pten+/− mice, Akt1, but not Akt2, deficiency dramatically inhibited the development of a range of tumours." (PMID 33276499, 2020). "In contrast, AKT1 expression in tumor samples is significantly higher than that in normal breast." (PMID 33311440, 2020). "PI3K pathway inhibitors did not decrease tumor growth in the two AKT1-mutated models, but HBCx-2 PDX responded to the mTOR inhibitor AZD2014 (TGI=86%, p=0.0001) and the dual inhibitor (mTOR and PIK3Ca) (TGI =70%, p=0.001)." (PMID 32042320, 2020). "LMTK3 and AKT1 each have a role in carcinogenesis and tumor progression." (PMID 33247671, 2020). "Cell-autonomous Akt2 ablation inhibited primary tumour formation whereas germline or inducible systemic deletion of Akt2 enhanced tumour development via elevated circulating insulin levels leading to hyperactivation of AKT1." (PMID 33276499, 2020).
tumor (continued). "AKT1 is involved in various biological processes, including cell metabolism, survival, and growth, and its abnormal expression correlated with poor prognosis of tumor patients." (PMID 32148531, 2020). "Finally, in vivo assays validated that circ-AKT1 promoted tumor growth and regulated miR-942-5p/AKT1 expression in CC." (PMID 32193155, 2020). "Co-treatment with cisplatin in mice carrying xenografts formed from knockdown of AKT2 (4T1 shAKT2) and AKT3 (4T1 shAKT3) in 4T1 cells dramatically attenuated tumor formation in mice after two weeks as compared with that of mice with knockdown of AKT1 (4T1 shAKT1) treated with cisplatin." (PMID 33227065, 2020). "AKT1 is mainly expressed in necrotic tumor tissue and located in nucleus." (PMID 33746736, 2020). "However, down-regulated Aldob in tumor tissues significantly decreased Akt1-immunoprecipitated Aldob and PP2A-C when compared to corresponding adjacent normal tissues, further suggesting that Aldob/Akt/PP2A signaling is involved in human HCC progression." (PMID 33275593, 2020). "Similarly, ectopic expression of Myr-Akt1 in GSCs expressing shWISP1 partially restored tumor growth and reduced the survival of mice bearing GSC-derived GBMs." (PMID 32541784, 2020). "The primary apoptotic response may be consistent with the activation of immune tumor-suppression by DCs induced in the Akt1 KO model." (PMID 33110146, 2020). "Again, this suggests that AKT1 polymorphisms are involved in tumor initiation rather than in processes of tumor progression, despite the I-131 activities used for treatment." (PMID 33112820, 2020). "In vivo assays validated that circ-AKT1 promoted tumor growth in CC." (PMID 32193155, 2020). "In the six patients with tumor alterations in PIK3CA, AKT1, or PTEN, the best overall response was SD < 4 months (n = 3, including the two patients with AKT1-altered tumors and one patient with PTEN K237fs mutation), progressive disease (n = 2), and non-evaluable (n = 1)." (PMID 33138866, 2020). "The subsequent investigation of S1PR1 revealed that it might also be a prognostic gene in LUAD (in TCGA cohort and GSE72094), with interactions with some well-known tumor genes such as AKT1, STAT3 and CXCR4." (PMID 33628734, 2020). "Akt1 depletion showed the most significant inhibition of tumor development and local invasion." (PMID 33110146, 2020). "As we observed microglia to directly interact with these AKT1+ cells and their processes, we speculate that microglia contribute to the establishment of a functional network between tumour cells by promoting the outgrowth of TMs." (PMID 31313988, 2019). "Recently, a novel Akt1/N-Ras-induced HCC mouse model was generated to elucidate crosstalk between tumor-associated antigen-specific T cells and stromal cells, and the underlying mechanisms governing immunosuppression in the HCC tumor microenvironment." (PMID 31581753, 2019). "Furthermore, an inverse correlation between AKT1 expression and tumor stages as well as metastatic nodal status was detected." (PMID 31752925, 2019). "Furthermore, we have recently shown that these cellular interactions are initiated during the earliest stages of tumour growth as they can already be observed between microglia and pre-neoplastic AKT1+ cells." (PMID 31313988, 2019). "AKT1 is involved in cellular growth, angiogenesis, and tumor cell invasiveness." (PMID 31284467, 2019). "Therefore, we believe that the low sensitivity of detecting AKT1 amplification in HCC1143/HCC1143BL FFPE cells at various tumor purity was due to DNA degradation produced during formalin fixation process." (PMID 31681791, 2019). "Gene expression levels measured relative to the adjacent normal cortex sample revealed numerous oncogenic driver genes with >2-fold higher expression in the tumour and clone samples, including genes encoding AURKA/B, CDK4/6, FGFR1, AKT1/2, MTOR, MET, PIK3C2A, WNT5A, SFRP4, and MYC." (PMID 30736342, 2019).
tumor (continued). "Studies have shown that FAM168A may mediate tumor cell proliferation and reduce apoptosis through AKT1/NFκB signaling pathway." (PMID 31291942, 2019). "The risk score was calculated as follows: risk score = 3.13 × (Notch4) ± 1.52 × (p-PKCα/β2) + 0.74 × (XIAP) + 0.58 × (CDK2) + 0.77 × (Akt1) + 0.74 × (TNM stage) + 1.20 × (vascular/lymphatic invasion) + 0.97 × (tumor size) + 0.61 × (age) + 0.58 × (histologic differentiation)." (PMID 31399040, 2019). "Furthermore, PI3K/Akt signaling and especially Akt through its isoforms Akt1 and Akt3—has been shown to play a regulatory role in the DNA damage response of tumor cells through the NHEJ and potentially HR repair mechanisms." (PMID 31847370, 2019). "In 786-O primary tumor cell line we observed decrease expression of genes of insulin-associated proteins (IRS2, CBL), transcription regulators (AEBP1), PI3 kinase signaling (AKT1, BCL2L1) as well as lipid metabolism genes (ACOX1)." (PMID 30929166, 2019). "AKT1 mutant clones, which were found in the minority of primary tumor samples, might sufficiently increase via clonal selection to detectable levels following surgery and adjuvant chemotherapy." (PMID 30898102, 2019). "Mutations in genes such as AKT1, BCOR, and PIK3R1 were also observed and these genes may also contribute to tumor development." (PMID 31101826, 2019). "There was very low or no expression of ki67 protein in residual tumor as compared to high expression of TFF3 in residual tumor cells suggesting that residual tumor cells have a low proliferating activity, this is supported by the high expression of Bcl2 and p-AKT-1 by residual tumor cells." (PMID 30744593, 2019). "In addition, PI3K subunit p85α and AKT1/2 were overexpressed, particularly in advanced tumor stages, and the phosphorylation level of mTOR and S6K1 was increased in CRC." (PMID 30754640, 2019). "In these cases, Ser473 phosphorylation may provide the tumor cell with a means to reduce the effectiveness of Akt1 inhibitors." (PMID 30205513, 2018). "Indeed, activation of Akt1 has been shown to accelerate tumorigenesis but suppresses tumor invasion in transgenic mouse models." (PMID 30445978, 2018). "Finally, to confirm and complete the signaling pathway for tumor incidence, we examined the mRNA expression of Pdk1 and Akt1 after DMBA administration." (PMID 30126855, 2018). "Similarly, AKT1 activation decreases tumor metastatic dissemination but promotes mammary tumorigenesis in mouse models, whereas AKT2 primarily increases tumor metastasis in those models." (PMID 30012111, 2018). "AKT1 also appears to mediate tumour development in Pten haplodeficient mice." (PMID 28513565, 2017). "Additionally, tumor tissues from patients with the GG genotype show increased AKT1 and Cyclin D1 expression compared with tumor tissues from patients with the AA and AG genotypes." (PMID 28045918, 2017). "Such a resultant decrease in FAK and Akt1 activation and inhibition of cell adhesion could attenuate the metastatic potential of shed tumor cells during surgery and increase tumor-free survival." (PMID 29228673, 2017). "In addition to stimulating tumor cell proliferation, growth and survival, Akt, especially Akt1, promotes DNA double-strand break (DSB) repair and clonogenic survival after irradiation." (PMID 29156644, 2017). "To enable prospective screening for the low prevalence AKT1 E17K mutation, we have developed and validated a competitive allele-specific TaqMan® PCR (castPCRTM) assay for mutation detection in formalin-fixed paraffin-embedded (FFPE) tumor tissue." (PMID 28472036, 2017). "As epithelial–mesenchymal transition (EMT) is a critical process in metastatic invasion, AKT1 induction of stem properties may confer an increase in invasive and metastatic potential of stem-like tumour cells." (PMID 28082369, 2017). "Some evidence points to a particular role of constitutive Akt1 activation in tumor promotion." (PMID 28903409, 2017).
tumor (continued). "The corresponding primary tumor from this patient showed a native form of the AKT1 gene." (PMID 28097440, 2017). "However, transgenic mammary expression of AKT1 or AKT2 alone in wild-type mice is insufficient to promote de novo tumour formation." (PMID 28082369, 2017). "Paradoxically, mouse model studies have shown that genetic alterations leading to constitutive activation of the PI3K/AKT1/mTORC1 signaling pathway may promote self-sufficiency in tumour growth." (PMID 28880250, 2017). "Thus, while overexpression of AKT1 promoted local tumor growth, downregulation of AKT1 or overexpression of AKT2 promoted peritumoral invasion and lung metastasis." (PMID 28287129, 2017). "The expression of AKT1 was significantly suppressed in tumor tissue (P = 0.0375)." (PMID 28301567, 2017). "We next examined the Akt1 expression levels in human tumor tissues and paired normal tissues." (PMID 27323412, 2016). "An increase in Akt1 phosphorylation was observed in 54.7% of the tumor tissue samples." (PMID 27650486, 2016). "In mice exposed to the lung carcinogen (NNK) loss of Akt1 or Akt2 decreased lung tumor multiplicity but did not decrease lung tumor volume while loss of Akt1 but not Akt2 in K-ras transgenic mice significantly decreased tumor multiplicity and tumor volume." (PMID 26654940, 2016). "Furthermore, we experimentally confirmed that miR-495 decreased tumor progression in vitro and in vivo by directly targeting Akt1." (PMID 27323412, 2016). "FHL2-induced increase in AKT1 may also be involved in mediating TGF-α/ERBBs autocrine/paracrine loops in GCT tumor cells." (PMID 27415427, 2016). "First, previous studies have only analysed virological factors or oncogenes associated with HCC progression, whereas our study showed that the concomitant expression of AKT1 and HBV CP mutations corresponding to the CP mutations that are clinically associated with HCC promote tumour progression." (PMID 27779207, 2016). "Finally, we showed that AKT isoforms 1, 2 and 3 are differentially upregulated in primary human HCCs and that overexpression of AKT correlates with worse tumor biology and pathologic features (AKT3) and prognosis (AKT1)." (PMID 27611696, 2016). "The presence of phosphorylated AKT1 was confirmed on histological tumor sections." (PMID 26137586, 2015). "In addition, we also explored the functions of Akt1 and Erk1/2 pathways in anti-tumor effects of fenofibrate." (PMID 24529079, 2014). "Cyto-protective pathways, such as Akt1 and/or Erk1/2 pathways might also be involved in anti-tumor effects of fenofibrate in TNBC." (PMID 24529079, 2014). "DU145-Neo cells produced similar bone reactions in our model, whereas overexpression of Akt1 completely reversed this phenotype to an osteolytic phenotype similar to PC-3 cells in this model, as evidenced by enhanced tumor growth and destruction of trabecular bone." (PMID 23902739, 2013). "Cytolysis of tumor targets was inhibited up to 90% when NK cells were cultured with fluvastatin by affecting i) receptor-mediated increase of the intracellular free calcium concentration, ii) activation of akt1/PKB and iii) perforin and granzyme release." (PMID 23667543, 2013). "In addition, ablation of Akt1 in MMTV-neu or MMTV-PyMT transgenics inhibited tumor formation while the ablation of Akt2 accelerated tumor formation." (PMID 23919516, 2013). "However, loss of Akt1 in the MMTV-neu and MMTV-PyMT transgenic mice had a much more dramatic impact on tumor onset than that observed in the MTB-IGFIR transgenic mice." (PMID 23919516, 2013). "Akt1 accelerates tumourigenesis through increased cell proliferation and is thus predominantly involved in the control of cell malignant transformation, whereas, simultaneously, Akt1 suppresses tumour invasion." (PMID 22842582, 2012). "PHLPP dephosphorylates S473 on Akt-1 which can induce apoptosis and inhibits tumor growth." (PMID 23006971, 2012).
tumor (continued). "Among the genes participating in the cascade of signal transfer in cell activated by leptin, the following ones: AKT1, STAT3, MCL1 were qualified as differentiating stage I and II and VEGFC, CCNDI the encoding genes respectively as differentiating III and IV stage neoplasm." (PMID 22363883, 2011). "Also, a dominant Akt1 mutant reduced latency of tumor formation in MMTV-Neu mice, while decreasing invasion and metastasis in this model." (PMID 21646685, 2011). "Here we demonstrated that several tumor types in zebrafish can be induced by transgenic expression of oncogenes, most likely due to co-expression of an oncogenic zebrafish Smoa1 and the constitutively active human AKT1." (PMID 19555497, 2009). "However, we observe a significant attenuation of tyrosine kinase signalling in tumours from the bitransgenic MMTV-myr-Akt1, MMTV-c-ErbB2 animals compared with tumours from the MMTV-c-ErbB2 animals, particularly with regard to ErbB3 and Src." (PMID 18700973, 2008). "The amount of Tyr452-phosphorylated Gab2 is dramatically higher in the c-ErbB2 tumours compared with the bitransgenic tumours suggesting that expression of activated Akt1 in the bitransgenic animals attenuates phosphorylation of Gab2 and subsequent docking of PI3K, which occurs in c-ErbB2 animals." (PMID 18700973, 2008). "Among the three human isoforms Akt1, Akt2, and Akt3, it has been suggested that Akt1 may have an important role in tumor initiation and tumor growth." (PMID 18184439, 2008). "Interestingly, tumours responded to trastuzumab by a sharp fivefold increase in phosphorylated AKT/PKB as well as a 3.5- and 5.3-fold increase in AKT1 and AKT2 mRNA levels, respectively." (PMID 18454161, 2008). "Furthermore, patients who had a poor outcome to endocrine therapy also had activated Akt1 in their tumor cells." (PMID 18184439, 2008). "Importantly, analysis of primary tumour tissues shows that Akt1 is frequently expressed and highly activated in patients." (PMID 16168126, 2005). "This paradox may be explained by either different sensitivity of the antibodies or by crossreactivity of the phospho-Akt-1 (ser473) antibody with another activated isoform present in the tumour, like Akt-2 or Akt-3." (PMID 11870534, 2002). "SFXN1 appears to be functionally linked with cell survival and growth promotion genes (AKT1, BCL2, MTOR) and pro-apoptotic components (BAX, CASP3), indicating its dual role in maintaining mitochondrial homeostasis and regulating cell fate decisions in tumor cells." (PMID 41399448, 2026). "Indeed, FOXO3a has been widely implicated in metastasis inhibition, suggesting that targeting AKT1 inhibition or FOXO3a elevation could be a promising strategy for suppressing tumor metastasis." (PMID 40223122, 2025). "Immunohistochemical staining confirmed the presence of CD45.1+ transferred T cells, showing that Akt2-OE CTLs could penetrate the tumor core, while control or Akt1-OE CTLs were primarily confined to the stroma (CD45.1 staining in brown, indicated by yellow arrow)." (PMID 40139836, 2025). "Another notable pan-tumor trial evaluating capivasertib is the phase II clinical trial (NCT03310541), which highlighted allele-specific differences in AKT activation and inhibitor sensitivity, reporting an ORR of 33% and stable disease in one of six patients with non-AKT1 E17K mutations." (PMID 40576713, 2025). "For HR+ HER2- BC seeking a second-line option, a targeted NGS BC panel is very useful to tell whether the tumor harbors an actionable mutation in critical BC-related genes, including ESR1, PIK3CA, AKT1, PTEN, as well as additional genes in the PI3K pathway or other synergetic pathways." (PMID 39796647, 2024).